HR (HR lysine demethylase and nuclear receptor corepressor)
Diseases named in the same sentence as HR in open-access papers (continued):
Sharing a sentence is not in itself a finding about the gene and the disease.
cancer (37 papers, 2012 to 2026). A tumor composed of atypical neoplastic, often pleomorphic cells that invade other tissues. "Over 59% of the PRAEGNANT cohort comprised patients with HR+/HER2- cancer, likely all having undergone some form of endocrine treatment; 21% of patients in this subgroup tested positive for actionable ESR1 mutations." (PMID 39839709, 2025). "Because patients with HR+/HER2– ABC/mBC are living longer with their cancer, our study findings showing that GHS/QoL was maintained for most patients treated with palbociclib plus ET while on active treatment is important." (PMID 40971858, 2025). "Although the complexity of cancer is well‐acknowledged, the implementation of precision cancer medicine until now has relied on discrete sets of isolated biomarkers (e.g. HR, HER2 and BRCA1/2 in breast cancer)." (PMID 39109701, 2024). "In comparison, the recent national comprehensive cancer network (NCCN) guidelines recommend that the use of multigene-expression assays should be considered in patients with HR+/HER2− eBC based on lymph node involvement." (PMID 36358784, 2022). "We analyzed National Cancer Database patients (HR+/HER2+/MBC) who were treated between 2010 and 2015." (PMID 31792304, 2019). "Therefore, we focused on the role played by HR genes in platinum-based chemotherapy sensitivity of cancer." (PMID 36591485, 2022). "This is likely attributable to the biological characteristics of the cancers, in which hormone receptor-positive/HER2-negative (HR+/HER2−) was the most prevalent subtype." (PMID 41142678, 2025). "All HR+/HER2- patients diagnosed between 2012 and 2022 who underwent surgery were selected from the Netherlands Cancer Registry." (PMID 41338056, 2025). "Based on the responsiveness of highly selective c-MET inhibitors to c-MET overexpressing cancer, we believe that the reduced PFS in the c-MET+ CTC high group suggests the potential effectiveness of c-MET inhibitors in treating patients with HR+/HER2− mBC." (PMID 38238761, 2024). "According to the 2017–2021 US SEER 22 database study, the percent of female breast cases by cancer subtype were HR+/HER2− (70%) and HR+/HER2+ (10%)." (PMID 39409083, 2024). "The majority of cancers (98.8%) were invasive ductal carcinomas: 16 (19.8%) were HR+/HER2− tumors, 8 (9.9%) were HR−/HER2+, and 16 (19.8%) were triple-positive and triple-negative, respectively." (PMID 39272859, 2024). "Among the top ERGs altered by deep CNAs, the majority showed amplifications, with the exception of HR, PHF11, and SETB2, which were commonly deleted in many cancer types." (PMID 32963031, 2020). "Although these clinical trials did not include patients with BC, c-MET inhibitors might improve the outcome of patients with HR+/HER2− with high c-MET+ CTCs, indicating the presence of cancer cells expressing c-MET." (PMID 38238761, 2024). "The percentages of patients with no known family history of a BRCA-related cancer were 24.6%, 27.8%, and 18.9% for the overall group, the TNBC subgroup, and the HR+/HER2-negative subgroup, respectively." (PMID 38817906, 2024).
HR also shares sentences with these, for which no sentence is quoted: infection (3 papers); cervical cancer (2); Ductal Carcinoma (2); lymph node metastases (2); adenoma (1); alopecia (1); Alopecia universalis (1); Arrhythmia (1); Carvajal syndrome (1); Cerebral ischemia (1); diffuse large B-cell lymphoma (1); ectodermal dysplasia (1); endothelial dysfunction (1); glioma (1); gynecologic tumors (1); heart failure (1); Hydrocephalus (1); hypotrichosis 6 (1); invasive carcinoma (1); Invasive Lobular Carcinoma (1); ischemia (1); lung adenocarcinoma (1); lung carcinoma (1); lung squamous cell carcinomas (1); migraine (1); myelodysplastic syndrome (1); myocardial infarction (1); Netherton syndrome (1); neutropenia (1); odonto-onycho-dermal dysplasia and (1).
A further 8 diseases each share a sentence with HR in 1 paper.